ENPP6 (ectonucleotide pyrophosphatase/phosphodiesterase 6)
Description:
Choline-specific glycerophosphodiesterase that hydrolyzes glycerophosphocholine (GPC) and lysophosphatidylcholine (LPC) and contributes to supplying choline to the cells. Has a preference for LPC with short (12:0 and 14:0) or polyunsaturated (18:2 and 20:4) fatty acids. In vitro, hydrolyzes only choline-containing lysophospholipids, such as sphingosylphosphorylcholine (SPC), platelet-activating factor (PAF) and lysoPAF, but not other lysophospholipids (By similarity).
Synonyms: MGC33971; NPP6
Tractability: Small molecule: a high-quality ligand is known. Antibody: UniProt places it where antibodies can reach, with high confidence; its Gene Ontology location is reachable by antibodies, with high confidence; UniProt predicts a signal peptide or a membrane-spanning region.
Target class: Enzyme; Phosphodiesterase
Gene: Protein-coding gene on chromosome 4 (184,088,706 to 184,221,230, reverse strand). Ensembl gene ENSG00000164303.
Subcellular location: Cell membrane
Subcellular location (Human Protein Atlas): Golgi apparatus
Pathways (Reactome):
Metabolism: Glycerophospholipid catabolism
Gene Ontology:
Molecular function: glycerophosphocholine cholinephosphodiesterase activity; phosphoric diester hydrolase activity; protein binding; glycerophosphodiester phosphodiesterase activity
Biological process: choline metabolic process; lipid metabolic process; glycerophospholipid catabolic process
Cellular component: extracellular exosome; extracellular region; plasma membrane
Genetic constraint (gnomAD): Loss-of-function variants: 31 observed, 41.98 expected, observed/expected ratio (o/e) 0.74, 90% interval 0.55 to 1. The upper end of that interval is the gene's LOEUF score, 1, which puts it in group 4 of 6, group 1 being the genes least tolerant of losing a copy. Missense variants: 522 observed, 563.66 expected, observed/expected ratio (o/e) 0.93, 90% interval 0.86 to 1. Synonymous variants: 197 observed, 214.18 expected, observed/expected ratio (o/e) 0.92, 90% interval 0.82 to 1.03.
Homologues: Orthologues: chimpanzee ENPP6 (99% identical), dog ENPP6 (92% identical), rabbit ENPP6 (92% identical), guinea pig ENPP6 (91% identical), macaque ENPP6 (91% identical), pig ENPP6 (91% identical), rat Enpp6 (87% identical), mouse Enpp6 (86% identical), tropical clawed frog irf2 (62% identical), zebrafish enpp6 (58% identical), Caenorhabditis elegans C01B10.9 (23% identical), Caenorhabditis elegans enpp-1 (23% identical), and 1 more. Paralogues in human: ENPP1 (31% identical), ENPP5 (31% identical), ENPP4 (31% identical), ENPP7 (30% identical), ENPP3 (29% identical), ENPP2 (26% identical).
Diseases named in the same sentence as ENPP6 in open-access papers:
ENPP6 is named in the same sentence as 13 diseases in open-access papers, as found by Europe PMC text mining. Sharing a sentence is not in itself a finding about the gene and the disease. The quoted sentences say what the papers report.
Alzheimer disease (1 paper, 2024). A progressive, neurodegenerative disease characterized by loss of function and death of nerve cells in several areas of the brain leading to loss of cognitive function such as memory and language. "In this context, ENPP6 expression in newly forming oligodendrocytes was found to play a critical role in motor skill learning, whereas genetic or proteomic data revealed some interesting links between ENPP6 and Alzheimer disease." (PMID 39125098, 2024).
hepatomas (1 paper, 2016). "Wild-type ENPP6 expressed in cultured hepatomas hydrolyzed both α- and β-GPC for the biosynthesis of PC." (PMID 26888014, 2016).
psychosis (1 paper, 2025). "Additionally, GWASs have identified loci associated with psychosis in AD, including ENPP6 and SUMF1." (PMID 40004081, 2025).
tumor (2 papers, 2022 to 2024). "The activities of CA1, ANXA10, and MUC1 were increased in LPS treated IBD enteroids compared to the LPS treated tumor enteroids, while the activities of BAAT, ACSL5, and ENPP6 were decreased." (PMID 35884586, 2022). "As control, stainings of ENPP6, MBP and LFB were observed in the non-tumour regions." (PMID 38764775, 2024). "Additionally, LPS treatment altered the ACSL5, ENPP6, and CA1 expression in the intestine and tumor enteroids." (PMID 35884586, 2022).
brain disorder (1 paper, 2025). A disease affecting the brain or part of the brain. "Of the significant reverse MR relationships, the brain disorders demonstrated associations with the increased expression of six proteins (PAMR1, MAVS, F11R, REN, GER and LEPR) and decreased expression of three proteins (TNFRSF4, BTN2A1, ENPP6)." (PMID 40456753, 2025).
cancer (1 paper, 2024). A tumor composed of atypical neoplastic, often pleomorphic cells that invade other tissues. "SMAD9 and ENPP6 are both involved in bone mineralization and could be involved in cancer like the gene BMPR1A (bone mineralization protein 1A), where variants predispose to CRC." (PMID 39543761, 2024).
ENPP6 also shares sentences with these, for which no sentence is quoted: breast carcinoma (1 paper); depression (1); glioneuronal tumours (1); multiple sclerosis (1); neuroepithelial tumours (1); osteomalacia (1); rickets (1).